IGF2 (insulin like growth factor 2)
Diseases named in the same sentence as IGF2 in open-access papers (continued):
Sharing a sentence is not in itself a finding about the gene and the disease.
myopia (2 papers, 2017 to 2023). "This network was composed primarily of genes involved in immune-mediated ECM remodeling, and included connections with many intermediate genes that have been strongly linked to myopia in previous targeted studies (e.g. MMP2, TGFB1, TGFB2, FGF2, INS, and IGF2)." (PMID 28852117, 2017). "Further analysis using an insulin microarray resulted that the levels of insulin and those related factors including IGF2, IGF-2R, IGF binding protein 1 (IGFBP-1), IGFBP-2, IGFBP-3, IGFBP-4 and IGFBP-6 were markedly increased in patients with pathogenic myopia as compared with the controls." (PMID 38203671, 2023).
pleural solitary fibrous tumor (2 papers, 2006 to 2019). A localized neoplasm of probable fibroblastic derivation, that arises from the pleura. "We herein report a case involving resection of an IGF2-producing pleural solitary fibrous tumor (SFT) using an AP." (PMID 32025979, 2019).
Pompe disease (2 papers, 2022 to 2023). "This has previously resulted in the design of an IGF2-tagged rhGAA chimeric protein that, compared with untagged rhGAA, showed superior clearance of glycogen after intravenous injection in a Pompe disease mouse model." (PMID 36284764, 2022). "Taken together, these results demonstrate superior efficacy of IGF2-tagged GAA over GAA when used as lentiviral gene therapy to treat skeletal muscle pathology in a Pompe disease mouse model." (PMID 36284764, 2022). "This indicated that epitope tagging with IGF2 provided strong improvement of lentiviral gene therapy for correcting murine Pompe disease at a dose suitable for clinical applications." (PMID 36284764, 2022). "Our results demonstrate that correction of Pompe disease pathology correlates with the strength of the preconditioning administrated prior to transplantation to maximize chimerism and thereby expression of the GAAco and IGF2.GAAco transgenes." (PMID 36284764, 2022). "Recent clinical trials showed transient hypoglycemia in patients with Pompe disease shortly after intravenous injection of recombinant IGF2.GAA at 10–20 mg/kg, but not at 5 mg/kg." (PMID 36284764, 2022).
retinoblastoma (2 papers, 2025). A malignant tumor that originates in the nuclear layer of the retina. "Insulin like growth factor 2 mRNA binding protein 3 (IGF2BP3)-mediated N6-methyladenosine of USP49 enhances carboplatin resistance in retinoblastoma by promoting autophagy through stabilizing Sirtuin 1 (SIRT1)." (PMID 41035649, 2025).
salivary carcinoma (2 papers, 2019 to 2024). "These mice develop at early age pelvic rhabdomyosarcomas with IGF2 overexpression, almost concomitantly to IGF2-independent salivary gland carcinomas." (PMID 30732578, 2019). "A murine model developing IGF2-overexpressing pelvic rhabdomyosarcoma, along with IGF2-independent salivary carcinoma, was used to investigate the efficacy and specificity of passive anti-IGFs antibody treatment." (PMID 30732578, 2019). "Neither off-target effects towards the IGF2-independent salivary carcinoma nor systemic effects on mice growth were observed." (PMID 30732578, 2019).
spina bifida (2 papers, 2014 to 2015). A congenital neural tube defect in which vertebrae are not fully formed. "The real-time qPCR assays indicated that in the spinal cords of mice fetuses with spina bifida, the Igf2 mRNA level was increased 1.84-fold compared to control (P = 0.0057, Student's t-test), but in human NTDs, this increment fold was 6.41." (PMID 25423083, 2014). "However, alterations affecting the ICR1-DMR and therefore in turn affecting IGF2 methylation and expression are only found in a minority of patients with BWS (~10%), making a judgment of increased spina bifida occurrence difficult." (PMID 25943194, 2015).
thyroid nodule (2 papers, 2022). A small circumscribed mass in the THYROID GLAND that can be of neoplastic growth or non-neoplastic abnormality. "Due to high homology of IGF-1 and IGF-2 to each other and to insulin, and involvement in cell proliferation, IGF-2 could also play a role in the development of thyroid nodules and/or thyromegaly." (PMID 35158824, 2022).
tyrosinemia (2 papers, 2022 to 2023). An autosomal recessive inherited metabolic disorder caused by mutations in the FAH, HPD, and TAT genes. "Moreover, in the mouse model of chronic liver injury caused by tyrosinemia or long-term treatments of CCl4, IGF2 can significantly promote hepatocyte proliferation and tissue repair in the condition of chronic liver injury." (PMID 38017373, 2023).
urothelial carcinoma (2 papers, 2000 to 2023). A malignant neoplasm derived from the transitional epithelium of the urinary tract (urinary bladder, ureter, urethra, or renal pelvis). "Among genes recorded in “Pathology” section in THPA, staining intensities of AKR1B1, TCHH, AKAP12, and IGF2 are distinctly higher in tissues from urothelial carcinoma than in normal bladder." (PMID 36512456, 2023).
abortion (1 paper, 2020). the ending of pregnancy by removing a fetus or embryo before it can survive outside the uterus. "This cross-sectional study aimed to investigate the role of 820A/G variant of the IGF-2 gene and the probability to recurrent spontaneous abortion (RSA) in southern Iran." (PMID 33062920, 2020).
acute lymphoblastic leukemia (1 paper, 2020). Leukemia with an acute onset, characterized by the presence of lymphoblasts in the bone marrow and the peripheral blood. "The RBP insulin-like growth factor 2 mRNA-binding protein 3 (IGF2BP3) has similarly been found to be overexpressed in mixed-lineage leukemia–rearranged (MLL rearranged) B-acute lymphoblastic leukemia (B-ALL) and to be associated with poorer outcomes and higher recurrence risks in these patients." (PMID 33228611, 2020).
acute pancreatitis (1 paper, 2020). An acute inflammatory process that leads to necrosis of the pancreatic parenchyma. "Igf1, like Igf2, is highly enriched in the mesenchyme-derived cells compared to non-mesenchyme cells and paracrine release of IGF1 from fibroblasts, which derive from the primitive mesenchyme, stimulate acinar cell proliferation during regeneration from acute pancreatitis." (PMID 33057429, 2020).
acute pneumonia (1 paper, 2024). "Abnormally high expression of IGF2 has been proved to facilitate lipopolysaccharide (LPS)-induced inflammatory damage and aggravate acute pneumonia." (PMID 39711843, 2024). "It is noteworthy that IGF2 knockout can inhibit the secretion of inflammatory cytokines to reduce LPS-induced cell damage in acute pneumonia." (PMID 39711843, 2024).
alcohol use disorder (1 paper, 2018). "As for alcohol use disorder, prenatal alcohol exposure alters one ASM of the H19/Igf2 locus, thereby causing about a 1.5-fold decrease of Igf2 transcripts." (PMID 30687383, 2018).
allergic disease (1 paper, 2023). An immune response that occurs following re-exposure to an innocuous antigen, and that requires the presence of existing antibodies against that antigen. "IGF2, a member of the growth hormone family involved in the immune pathogenesis of allergic diseases, is synthesized from an imprinted gene located in the p15.5 region on chromosome 11." (PMID 38037054, 2023).
ameloblastoma (1 paper, 2020). The most common odontogenic tumor, arising from the epithelial component of the embryonic tooth and usually affecting the molar-ramus region of the mandible or maxilla. "Importantly, insulin like growth factor 2 (IGF2), a member of KRAS‐responsive genes, enhances the proliferation of an ameloblastoma cell line AMU‐AM1 with BRAF mutation." (PMID 32096304, 2020). "Moreover, our qRT‐PCR analysis, as well as microarray data, showed that mRNA expression levels of INHBA, IGF2, and TLR2, all of which are classified into the KRAS‐responsive gene sets, significantly increase in ameloblastoma compared to normal counterpart tissues." (PMID 32096304, 2020). "Although IGF2 is not likely a specific growth factor for ameloblastoma, our data are the first to demonstrate the positive effect of IGF2, which is classified into KRAS‐responsive gene sets, on ameloblastoma cells." (PMID 32096304, 2020).
atrial septal defect (1 paper, 2025). Interauricular communication is a congenital malformation characterized by a communication between the atrial chambers of the heart. "The most common cardiac defects in IGF2 were ventricular septal defect (44.4%, 4/9) and atrial septal defect (22.2%, 2/9)." (PMID 41430624, 2025).
brachydactyly (1 paper, 2012). A disease characterized by the presence of brachydactyly, including syndromic and non-syndromic forms. "Accordingly, we speculate that in our patient a change in the methylation pattern of ZAC1 modifies the expression of H19 and/or IGF2 and gives rise to BWS phenotype, and perhaps even to the brachydactyly, because such a gene is highly expressed in chondrogenic tissue." (PMID 22974175, 2012).
breast adenocarcinoma (1 paper, 2016). "As expected, we found upregulation of H19, IGF2 and HMGA1 following HMGA1P7 overexpression in MCF7 cells (human breast adenocarcinoma cell line)." (PMID 27874091, 2016).
breast disease (1 paper, 2010). "Studies on genetic variants of IGF2 in relation to breast disease are few, and to our knowledge, the present study is the first to look at IGF2 polymorphisms in relation to levels of mammographic density, IGF1 and IGFBP3." (PMID 20302654, 2010).
carcinoma in situ (1 paper, 2012). "From these experiments, we concluded that elevating Igf2 expression accelerated tumour progression and induced carcinoma in situ development in the context of constitutive β-catenin activation." (PMID 22952916, 2012).
celiac disease (1 paper, 2019). An autoimmune genetic disorder with an unknown pattern of inheritance that primarily affects the digestive tract. "Third, we corrected the observed methylation degree based on the estimated calibration curves in two specific target regions (KCNQ1OT1 and H19/IGF2) important for their BWS clinical diagnostic value and in three target genes that have been associated with susceptibility to celiac disease." (PMID 31049595, 2019).
central precocious puberty (1 paper, 2018). "Since members of the IGF family are involved in the onset of puberty, we aimed to identify polymorphisms in insulin (INS), IGF-1, IGF-2, IGF-1 receptor (IGF1R), IGR2R, and IGF binding protein 3 (IGFBP-3) that may alter the risk for development of central precocious puberty." (PMID 30249230, 2018).
childhood tumors (1 paper, 2017). "Loss of IGF2 imprinting (LOI) with biallelic expression of IGF2 is a hallmark of many human tumors, especially childhood tumors, and of cancer stem cells." (PMID 27486969, 2017).
chordoma (1 paper, 2016). Chordomas are rare malignant tumors arising from embryonic remnants of the notochord in axial skeleton. "Another IHC study detected IGF-1R, IGF-1, and IGF-2 in 76, 90, and 50% of chordomas, respectively, with one-third showing moderate to strong IGF-1R, as in our study, and a significant correlation between IGF-1R staining intensity and primary tumor volume." (PMID 27200287, 2016).
chronic hepatitis B (1 paper, 2011). "In patients with chronic hepatitis B, HBV X protein stimulated IGF-2 expression by binding to the fetal promoter of IGF-2, therefore directly stimulating fetal transcript expression of IGF-2 in HCC." (PMID 21729319, 2011).
clear cell renal cell carcinoma (1 paper, 2024). "As LOI studies in clear cell renal cell carcinoma (ccRCC) are limited to IGF2, we performed a genome-wide analysis in 128 kidney normal solid tissue and 240 stage 1 ccRCC samples (TCGA RNA-seq data) to screen for canonical LOI in early oncogenesis." (PMID 39199324, 2024).
clear cell sarcomas of the kidney (1 paper, 2023). "In a group of 30 cases of clear cell sarcomas of the kidney, 43% had IGF2 overexpressed considered IGF2 LOI, with retention of normal H19 expression." (PMID 37686532, 2023).
colon adenoma (1 paper, 2012). An adenoma that arises from the colon. "Indeed, increasing Igf2 levels through LOI (heterozygous deletion of H19) or with a keratin 10 promoter increases the number and size of colon adenomas as well as malignant progression in APCMin/+ mice." (PMID 22952916, 2012).
Cryptococcal meningitis (1 paper, 2022). Meningeal inflammation produced by cryptococcus neoformans, an encapsulated yeast that tends to infect individuals with acquired immunodeficiency syndrome and other immunocompromised states. "These evidence indicate that IGF2 is critical for the pathogenesis of cryptococcal meningitis, but further research is needed." (PMID 35378790, 2022).
cystic renal disease (1 paper, 2025). "IGF2 overexpression in the IC1 subtype demonstrated striking nephromegaly, and the downregulation of p57KIP2 in the IC2 subytpe (loss of KvDMR1 methylation which might downregulate p57KIP2 expression) produced cystic renal disease." (PMID 40518523, 2025).
demyelinating disease (1 paper, 2021). A broad group of disorders that affect the myelin sheaths that cover the neurons. "In these top 10 proteins, IGF2, IGBP7 and SST were the proteins with large fold changes (FC=4.43, 2.60 and 0.17).Besides, we found that IGF2, IGFBP7 and SST are related to demyelinating disease in previous research." (PMID 34489947, 2021).
dwarfism (1 paper, 2019). "Insulin-like growth factor-2 mRNA-binding protein-1-deficient mice show dwarfism, impaired gut development, and downregulated IGF2 expression level at the embryonic stage." (PMID 31658691, 2019).
emphysema (1 paper, 2024). "The current study aims to verify the role of IGF2 signaling in the associated development of emphysema and cancer and develop effective pharmaceuticals for the diseases using animal models that recapitulate the characteristics of these chronic diseases." (PMID 38902841, 2024). "Using AT2-specific insulin receptor knockout mice, we verified the causative role of sustained IGF2 signaling activation in AT2s in emphysema development." (PMID 38902841, 2024). "Additionally, our results highlight the use of specifically targeted therapies that control the bioavailability of IGF2 as a potential preventive strategy to reduce the risk of emphysema and cancer." (PMID 38902841, 2024). "Next, we assessed whether IGF2 expression was implicated in emphysema development in NB-exposed mice." (PMID 38902841, 2024). "We demonstrated that chronic inflammation in the lungs induced by NB exposure shunts AT2 proliferation from a resource for alveolar barrier regeneration to a common origin of emphysema and tumor development through sustained activation of IGF2 signaling." (PMID 38902841, 2024). "Our work confirms sustained IGF2 signaling activation in AT2s couples impaired lung repair to the concurrent development of emphysema and cancer in mice." (PMID 38902841, 2024). "Next, we assessed the effects of IGF2 deprivation strategies on NB-induced pulmonary emphysema and tumor development." (PMID 38902841, 2024). "Notably, the severity of emphysema assessed by MLIs was significantly correlated with the degree of AT2s expressing IGF2." (PMID 38902841, 2024). "AT2-specific overexpression of IGF2 and IGF-1R/IR signaling activation was also observed in emphysema and tumor lesions of the lungs in patients with a history of TS." (PMID 38902841, 2024).
endocrine cancer (1 paper, 2014). "Insulin-like growth factor 2 (IGF2) overexpression is an important molecular marker of adrenocortical carcinoma (ACC), which is a rare but devastating endocrine cancer." (PMID 25089899, 2014).
endometrial tumors (1 paper, 2014). "Epidemiological as well as clinical and experimental data identified the insulin-like growth factors (IGF1, IGF2) as important players in gynecological cancers in general, and endometrial tumors in particular." (PMID 24904527, 2014).
ependymal tumor (1 paper, 2022). A group of neoplasms which arise from the ependymal lining of the cerebral ventricles and from the remnants of the central canal of the spinal cord. "Cytoplasmic staining for IGF2 was also observed in these cells, suggesting that MN1-BEND2 or other ependymal tumors may originate from similar immature ependymal cells derived from vRG9,52." (PMID 35440587, 2022).
epithelial ovarian tumors (1 paper, 2014). "Our prior study of IGF2 protein expression using a tissue microarray of epithelial ovarian tumors indicated that high tissue expression levels of IGF2 were associated with a shortened interval to progression/recurrence." (PMID 24932685, 2014).
folate deficiency (1 paper, 2023). A nutritional condition produced by a deficiency of FOLIC ACID in the diet. "Animal research showed that paternal folate deficiency at mating could influence fetal brain DNA methylation and insulin-like growth factor-2 (ILGF-2) expression." (PMID 37447170, 2023).
giant cell tumor (1 paper, 2024). A benign, intermediate, or malignant tumor that arises from the bone or soft tissue. "IMP3 and IGF2 might be potential biomarkers for GCT of the spine in regulating the angiogenesis of giant cell tumor of bone and predicting patients’ prognosis." (PMID 39795567, 2024).
Granuloma (1 paper, 2019). A compact, organized collection of mature mononuclear phagocytes, which may be but is not necessarily accompanied by accessory features such as necrosis. "Nevertheless, Igf2 and Cebpa were clearly regulated differently in Spalax fibrosarcoma samples than in the granuloma samples." (PMID 30621584, 2019). "The cell growth genes Igf2 and Cebpa are also up-regulated in granuloma." (PMID 30621584, 2019).
hepatocellular adenoma (1 paper, 2023). A benign epithelial neoplasm arising from the hepatocytes. "In contrast, hepatocellular adenomas expressed mostly adult IGF2 transcripts." (PMID 37932266, 2023).
herpesvirus infection (1 paper, 2022). "The other significant pathways are Kaposi’s sarcoma-associated herpesvirus infection (steered by ZFP36 and CXCL2), PI3K-Akt signaling pathway and the proteoglycans in cancer pathways (steered by IGF2 and TLR2)." (PMID 35277538, 2022).
Hirschsprung disease (1 paper, 2018). Hirschsprung disease (HSCR) is a congenital intestinal motility disorder that is characterized by signs of intestinal obstruction due to the presence of an aganglionic segment of variable extent in the terminal part of the colon. "This study revealed that miR‐483‐3p derived from IGF2 was associated with Hirschsprung's disease by targeting FHL1 and may provide a new pathway to understand the aetiology of HSCR." (PMID 30073757, 2018). "Consistent with miR‐483‐3p, IGF2 was also down‐regulated in HSCR tested via qRT‐PCR and it enhanced us to reveal whether the dysregulation of IGF2 has some influences on the occurrence or development of congenital megacolon or not." (PMID 30073757, 2018).
HIV encephalitis (1 paper, 2013). "Immunohistochemistry of human brain tissues showed that nonparenchymal cells (vessels and meninges), as well as parenchymal microglia and macrophages were positive for IGF1, in both HIV encephalitis and control brains, while IGF2 was undetectable." (PMID 23497056, 2013).
HIV-associated neurocognitive disorder (1 paper, 2015). HIV-associated neurocognitive disorder (HAND) remains a common complication of HIV infection in the combination antiretroviral therapy (ART) era. "We also determined whether IGF1 or IGF2 deficiency is associated with HIV-associated neurocognitive disorder (HAND) and whether the levels of soluble IGF2R (an IGF scavenging receptor, which we also have found to be a cofactor for HIV infection in vitro) correlate with HIV viral load (VL)." (PMID 25890304, 2015).
hydrops (1 paper, 2010). "However, close inspection of individual profiles revealed that within the SCNT-hydrops group, there were individuals who showed aberrant hypo- or hypermethylation, particularly in the IGF2 exon 10 DMR, KCNQ1OT1, SNRPN and HAND1 regions." (PMID 20205951, 2010).
iron overload (1 paper, 2023). "Hence, IGF2 and ZFP27 may be a potential therapeutic target in PD caused by iron overload." (PMID 37668106, 2023).